ANKRD18B (ankyrin repeat domain 18B)
Synonyms: bA255A11.3; bA255A11.5
Tractability: PROTAC: ubiquitination databases record sites on it.
Gene: Protein-coding gene on chromosome 9 (33,524,251 to 33,608,848, forward strand). Ensembl gene ENSG00000230453.
Genetic constraint (gnomAD): Loss-of-function variants: 62 observed, 86.04 expected, observed/expected ratio (o/e) 0.72, 90% interval 0.59 to 0.89. The upper end of that interval is the gene's LOEUF score, 0.89, which puts it in group 3 of 6, group 1 being the genes least tolerant of losing a copy. Missense variants: 987 observed, 1,080.4 expected, observed/expected ratio (o/e) 0.91, 90% interval 0.87 to 0.96. Synonymous variants: 343 observed, 374.62 expected, observed/expected ratio (o/e) 0.92, 90% interval 0.84 to 1.
Homologues: Orthologues: tropical clawed frog ankrd7 (21% identical), Caenorhabditis elegans lem-3 (10% identical), Drosophila melanogaster CG8679 (9% identical), zebrafish si:ch211-272n13.3 (8% identical), Caenorhabditis elegans F44E5.15 (4% identical), Drosophila melanogaster CG42391 (3% identical), Caenorhabditis elegans K07D4.2 (2% identical). Paralogues in human: ANKRD18A (83% identical), ANKRD26 (44% identical), ANKRD20A1 (32% identical), ANKRD30B (22% identical), ANKRD62 (22% identical), ANKRD30A (22% identical), ANKRD30BL (10% identical).
Diseases named in the same sentence as ANKRD18B in open-access papers:
ANKRD18B is named in the same sentence as 8 diseases in open-access papers, as found by Europe PMC text mining. Sharing a sentence is not in itself a finding about the gene and the disease. The quoted sentences say what the papers report.
lung carcinoma (2 papers, 2017 to 2021). "Recently, CpG island hyper-methylation of ANKRD18B was associated with decreased expression of ANKRD18B in lung cancer tissues and cell lines compared to normal lung tissues." (PMID 28416970, 2017). "ANKRD18B is a member of ANKRD family that functions in the occurrence of cancer, evidence that over-expression of ANKRD18B suppressed the growth of lung cancer cells has been reported." (PMID 34416861, 2021).
breast carcinoma (1 paper, 2022). "GEPIA analysis showed ANKRD18B mRNA upregulation in tumor samples and associated with low survival in Her2 + ve breast cancer." (PMID 36474139, 2022). "We checked the expression of ANKRD18B in breast cancer patients using GEPIA and found it to be upregulated." (PMID 36474139, 2022). "Thus, ANKRD18B has an oncogenic role in breast cancer, and ST08 and ST09 regulate its expression via methylation." (PMID 36474139, 2022).
cervical cancer (1 paper, 2023). A primary or metastatic malignant neoplasm involving the cervix. "This upregulation in tumor tissues suggests a potential role of ANKRD18B in cervical cancer progression." (PMID 37701623, 2023). "Although the exact role of ANKRD18B in this process is still unclear, its significant alteration following Doxorubicin treatment, as shown in our study, suggests that it may be implicated in the response to therapy in HPV-positive cervical cancers." (PMID 37701623, 2023).
cervical squamous cell carcinoma (1 paper, 2023). A squamous cell carcinoma arising from the cervical epithelium. "In our analysis of the TCGA-CESC (Cervical Squamous Cell Carcinoma and Endocervical Adenocarcinoma) dataset, ANKRD18B emerged as a gene of significant interest." (PMID 37701623, 2023).
ovarian carcinoma (1 paper, 2022). A malignant neoplasm originating from the surface ovarian epithelium. "In taxol-resistant ovarian cancer cells, NEB along with DCDC2, ANKRD18B, ALDH1A1, and ITGBL1 were overexpressed suggesting the involvement of these AR-related genes in taxol resistance." (PMID 35975176, 2022).
tumor (2 papers, 2022 to 2023). "We found that the expression of ANKRD18B was significantly elevated in tumor tissues compared to their normal counterparts (p < 0.05)." (PMID 37701623, 2023). "The marked upregulation of ANKRD18B in response to Doxorubicin treatment, as revealed by our transcriptomic analysis, points towards a potential mechanistic role of this gene in the anti-tumor action of Doxorubicin." (PMID 37701623, 2023).
ANKRD18B also shares sentences with these, for which no sentence is quoted: cancer (1 paper); endocervical adenocarcinoma (1).